COL1A1 (collagen type I alpha 1 chain)
Diseases named in the same sentence as COL1A1 in open-access papers (continued):
Sharing a sentence is not in itself a finding about the gene and the disease.
myopia (continued). "We genotyped rs2075555 and rs2269336 SNPs in COL1A1 in a Ha n Chinese group composed of 697 high myopia patients and 762 normal controls." (PMID 22219633, 2011). "The collagen type I (COL1A1) gene has been described as playing an important role in the pathogenesis of experimental myopia." (PMID 22219633, 2011). "Furthermore, 3-IAA treatment attenuated the myopia-induced decrease in COL1A1 levels in the sclera of these mice." (PMID 39187483, 2024). "Furthermore, its content is decreased by form-deprived and minus-lens-induced myopia, which reduces COL1A1 expression and increases its degradation by MMP." (PMID 33291388, 2020). "The results indicate that higher levels of DNA methylation in the COL1A1 promoter may inhibit scleral collagen synthesis and contribute to the development of myopia." (PMID 23559860, 2013). "Extracellular matrix components such as collagen type I alpha 1 (COL1A1), collagen type II alpha 1 (COL2A1), lumican (LUM), decorin (DCN) and epiphycan (EPYC or DSPG3) have been previously assessed for genetic associations with myopia." (PMID 23077567, 2012). "One report links COL1A1 polymorphisms with high myopia in Japanese subjects, but others do not confirm this." (PMID 22690110, 2012). "COL1A1 is located on chromosome 17q21 where the myopia 5 (MYP5) locus was identified." (PMID 22219633, 2011). "The study identified an absence of association between COL1A1 polymorphisms and high myopia in the Japanese population." (PMID 22219633, 2011). "Furthermore, we demonstrated that pharmacological inhibition of choroidal MC degranulation effectively attenuated myopia progression and suppressed scleral remodeling by preventing the downregulation of COL1A1 and the upregulation of matrix metallopeptidase 2 (MMP-2)." (PMID 41222199, 2025). "In addition, brimonidine might affect the development of myopia by upregulating Col1a1 and Mmp2 gene expression in the retina." (PMID 34256866, 2021). "Thus, epigenetic changes such as CpG methylation of COL1A1 may play a more meaningful role in low and moderate myopia." (PMID 22690110, 2012). "The COL1A1 gene is speculated to be a susceptibility gene for high myopia, as it is located in MYP5 (17q21–22) of high myopia candidate locus and is downregulated during myopia in animal models." (PMID 22690110, 2012). "After intravitreal injection of rhBMP2, compared with the myopia group, TIMP2 and Col1A1 expression was significantly increased in the MD and HD groups (p < 0.05), while there was no significant change in the LD group (p > 0.05)." (PMID 40375931, 2025). "The expression of COL1A1, the main component of the scleral ECM, exhibited decreased expression during the development of myopia." (PMID 39187483, 2024). "However the mechanism of COL1A1 modulation in myopia still remains unclear." (PMID 22690110, 2012). "Furthermore, LF suppressed lens-induced myopia (LIM)-induced MMP-2 activation, besides increasing COL1A1 expression." (PMID 33291388, 2020). "However, there have been no reports on changes in COL1A1 methylation or that of other genes in the development of myopia." (PMID 22690110, 2012). "This shows that form deprivation myopia in mice may also affect methylation of COL1A1 in MD-C eyes, resulting in the absence of significant differences in total methylation between the MD-T and MD-C eyes." (PMID 22690110, 2012).
sarcoma (18 papers, 2011 to 2025). A usually aggressive malignant neoplasm of the soft tissue or bone. "Analysis of the TCGA sarcoma dataset suggested that TGFB1 mRNA expression (z-score) was positively correlated with COL1A1 expression (P < 0.0001, Pearson r: 0.3991)." (PMID 39574893, 2024). "The patients with COL1A1-PDGFB-rearranged sarcoma tend to be older than those with NTRK-rearranged sarcoma." (PMID 39064514, 2024). "Most sarcoma-associated fusion genes such as SYT-SSX1/SSX2, BCOR-CCNB3, EWS-FLI1, PAX3-FOXO1 and COL1A1-PDGFB produce functional proteins." (PMID 25300797, 2014). "However, most of these tumors have been recently reclassified as genetically defined tyrosine kinase fusion associated sarcomas including in particular NTRK and COL1A1::PDGFB fusions." (PMID 39196362, 2024). "Among them, COL1A1, PDGFRB, and SPARC were confirmed as sarcoma-related genes using the GEPIA database." (PMID 41040657, 2025). "Then, we analyzed the expression of biomarkers of osteoblasts (COL1A1, BGLAP and RUNX2), chondrocytes (COL2A1, COMP and SOX9) and sarcoma (POSTN and DCN), adipocyte (LPL and PPARG) and BMSCs." (PMID 39715773, 2024). "Through this analysis, COL1A1, PDGFRB, and SPARC were identified as sarcoma-related genes." (PMID 41040657, 2025). "In comparison to other types of sarcoma, FAM98A and COL1A1 had good OS specificity." (PMID 35151325, 2022). "Cytogenetic and molecular genetic analyses have shown that many of these sarcomas are characterized by recurrent chromosomal translocations resulting in highly specific fusion genes (e.g., FUS-DDIT3 in MLS, FUS-CREB3L2 in LGFMS, EWSR1-NR4A3 in EMC, and COL1A1-PDGFB in myxoid DFSP)." (PMID 22567356, 2011).
colon carcinoma (17 papers, 2005 to 2025). "In colon cancer, the level of collagen expression is the key indicator to predicting the OS and risk, especially the types of COL1A1, COL1A2, COL3A1, COL4A3, and COL4A6." (PMID 36142424, 2022). "Results from our study show a potential value of SFRP2 and COL1A1 to identify patients at high risk of colon cancer recurrence and metastatic disease." (PMID 33670920, 2021). "The expression of ECM proteins such as Fibronectin 1 (FN1) and collagen type 1 α 1 (COL1A1) have been implicated in promoting migration and invasion in colon cancer." (PMID 34885111, 2021). "The high expression of COL1A1 in colon cancer is significantly related to serous membrane infiltration, lymphatic metastasis, and hematogenous metastasis." (PMID 36498737, 2022). "We investigated protein expression of COL1A1 by immunohistochemistry (IHC) staining of colon cancer tissue, pAT and distal adipose tissue in 5 colon cancer patients." (PMID 33670920, 2021). "The IHC staining of COL1A1 was strongest in colon cancer tissue with thick bundles of collagen, becoming less intense in pAT, and weaker at distant adipose tissue." (PMID 33670920, 2021). "Col1a1 expression is upregulated in colon cancer and in other hyperproliferative disorders, but normal colonic expression has not been previously reported." (PMID 22496968, 2012). "COL1A1 may represent a stromal prognostic biomarker and therapeutic target in colon cancer." (PMID 33670920, 2021). "BGN, COL1A1, and SFRP2 were upregulated DEGs at 1-cm tissue in our study and these three DEGs were present in the stromal gene group of Connell model related to colon cancer recurrence." (PMID 38062443, 2023). "Numerous studies have shown the proliferative role of collagen signals, COL1A1 and COL11A1, in gastric, breast and colon cancers." (PMID 34824625, 2021). "Similarly, CDSE pretreatment induced COL1A1 and COL1A2 mRNA expression in fresh colonic tissues from colon cancer patients." (PMID 35840034, 2022). "Moreover, miR-642a-5p was found to inhibit colon cancer cell migration, invasion, and EMT by targeting COL1A1." (PMID 36545127, 2022). "In addition, COL1A1 and COL1A2 might forecast bad clinical results in gastric and colon cancer patient." (PMID 35646104, 2022). "COL1A1, which is upregulated in COAD, may be a biomarker for colon cancer progression." (PMID 32211396, 2020).
bladder cancer (16 papers, 2016 to 2025). "We recently validated these findings in bladder cancer, showing lower COL1A1 protein and RNA levels in normoxia (21%O2) than in hypoxia (0.2% O2)." (PMID 40792276, 2025). "Additionally, we assessed the overall survival of bladder cancer patients with high/low COL1A1/COL1A2 expression by analyzing the Cancer Genome Atlas Program (TCGA) databases." (PMID 35694719, 2022). "Furthermore, analysis of the TCGA database correlated a survival benefit with low levels of COL1A1/COL1A2 in bladder cancer patients." (PMID 35694719, 2022). "COL1A1 was reported to be involved in the differentiation and metastasis of human bladder cancer." (PMID 36211008, 2022). "In breast invasive carcinoma (BRCA), prostate adenocarcinoma (PRAD), colon adenocarcinoma (COAD), and bladder cancer (BLCA), COL1A1 expression was higher in the advanced N stage than in the N0 stage." (PMID 39191749, 2024). "Researchers have found that the knockdown of COL1A1 can inhibit the EMT process through the TGF-β signaling pathway, thereby inhibiting the invasion and metastasis of liver cancer and bladder cancer." (PMID 34395525, 2021). "COL4A2 expression is positively correlated with the presence of macrophage and dendritic cell infiltration in cervical-cell cancer, while COL1A1 is positively correlated with tumor infiltration levels of macrophages and CD4+ T cells in bladder cancer." (PMID 33790966, 2021). "Previous study shown that COL1A1 was correlated positively with the tumor infiltration levels of CD4+ T cells and macrophages in Bladder Cancer." (PMID 33850663, 2021). "In addition, the COL1A1 and FN1 genes may affect the progression of bladder cancer by regulating the ECM-receptor interaction." (PMID 38678587, 2024).
myocardial infarction (16 papers, 2015 to 2025). Gross necrosis of the myocardium, as a result of interruption of the blood supply to the area, as in coronary thrombosis. "In addition, CAR3 deficiency dampened the mRNA levels of ECM-related genes Col1A1, Col3A1, Postn and Acta2 after myocardial infarction." (PMID 38481818, 2024). "miR‐30a has been shown to attenuate cardiac fibrosis in myocardial infarction rats by reducing the Col1a1/Col3a1 ratio." (PMID 39592912, 2025). "Previous studies have shown that quercetin restrains the level of fibrotic proteins including TGF-β1, α-SMA, Col1a1, and Col3a1 in heart tissue of myocardial infarction model." (PMID 38476331, 2024). "Here, we found that, compared to control mouse hearts, αSMA and Col1a1 were significantly elevated in the hearts of ATF6 knockout (KO) mice subjected to myocardial infarction." (PMID 32085622, 2020). "MiR-29b and miR-205-3p could downregulate the expression of TGF-β1, Col1a1, and Col3a1, so as to resist MF following myocardial infarction." (PMID 38476331, 2024). "Moreover, TGF-β1 is overexpressed in the heart in a high-cholesterol-fed porcine model of myocardial infarction, and its downstream Smad2 and Smad3 are activated, thereby increasing collagen synthesis and the levels of Col1a1, Col3a1, and α-SMA." (PMID 34485393, 2021). "Macrophage depletion markedly decreased the number of Mac3+ Col1A1+ cells in the heart following myocardial infarction, and therapeutic control of MMT might positively influence the fibrotic reaction postmyocardial infarction and other cardiovascular pathological conditions." (PMID 39445007, 2024). "The genes coding for type IA1 collagen (COL1A1) and type VIA3 collagen (CLA6A3) were increased in XH, which are comparable to animal models of myocardial infarction." (PMID 33451076, 2021). "At 4 weeks after myocardial infarction, however, CILP1 levels are very strongly elevated (10-fold) while COL1A1 levels at this time-point are already decreasing." (PMID 29167509, 2017). "COL1A1 and COL3A1 mRNA as well as collagen cross-linking enzymes were found to be upregulated by the transcription factor Zinc Finger E-Box Binding Homeobox 1 (ZEB1) in the context of myocardial infarction." (PMID 37373151, 2023). "Two matrikines are derived from COL1A1: DGGRYY peptide that can inhibit human neutrophil activation by collagen, and COL1 matricryptin p1158/1159 that has recently shown promising results in generating new ECM and stimulating angiogenesis post myocardial infarction." (PMID 32210969, 2020). "The time frame of induction of CILP1 following myocardial infarction shows that after 5 days CILP1 induction is not significant, in contrast to the strongly increased COL1A1 (almost 30-fold) or CTGF (almost 4-fold)." (PMID 29167509, 2017). "CILP1 expression was determined in mouse LV infarct tissue (MI) and remote non-infarcted area (RA) at 5 days and 4 weeks following myocardial infarction and compared to connective tissue growth factor (CTGF), collagen type I (COL1A1), TGFβ1 and TGFβ3." (PMID 29167509, 2017).
osteogenesis imperfecta type 1 (16 papers, 2010 to 2026). Osteogenesis imperfecta type I is a mild type of osteogenesis imperfecta (OI), a genetic disorder characterized by increased bone fragility, low bone mass and susceptibility to bone fractures. "Variants in COL1A1 are associated with bone disorders, including osteogenesis imperfecta types 1–4." (PMID 39276275, 2024). "As such, a decreased bone formation was clearly indicated by the lower P1NP concentration in Mov13 mice which corresponds with the lower concentration found in HI OI type 1 patients and Col1a1 ± 365 mice." (PMID 36967771, 2023). "The frequently observed molecular diagnoses (observed in more than one patient) include Osteogenesis Imperfecta Type I (COL1A1, MIM:166200), Neurofibromatosis, Type I (NF1, MIM:162200) and Marfan Syndrome (FBN1, MIM:154700)." (PMID 35346302, 2022).
tendinopathy (15 papers, 2015 to 2025). "Given, however, limited research on these variants in tendon pathology, we analyzed the impact of COL1A1 polymorphisms on the tendinopathy phenotype and the effectiveness of platelet-rich plasma (PRP) treatment for tennis elbow." (PMID 39684930, 2024). "This study underscores the influence of COL1A1 genetic variants on the clinical phenotype of patients with tendinopathies and highlights gaps in our understanding of the role these variants play in the molecular phenotype of tendons determination." (PMID 39684930, 2024). "In the light of current knowledge, well-established factors of susceptibility to tendinopathy are the polymorphic variants of collagen, type I, alpha-1 (COL1A1), collagen, type V, alpha-1 (COL5A1) and matrix metalloproteinase 3 (MMP3) genes." (PMID 35743573, 2022). "In line with aberrant matrix turnover generally featured in tendinopathy, the transcripts of the following genes were significantly increased in the tendinopathic samples: COL1A1, COL1A2, COL18A1." (PMID 39918402, 2025). "Here,a new LNP platform for simultaneous delivery of SMAD3 siRNAand COL1A1 mRNA was developed by using microfluidics technology asa potential therapeutic approach for treating tendinopathy." (PMID 39144399, 2024). "In the moderate tendinopathy group, an increased COL1A1:COL3A1 ratio was found in PRP cultures and even moreso after LP-PRP injection." (PMID 36769065, 2023). "To investigate the effect of nesfatin-1 on HO in tendinopathy, we detected the expression of osteogenic markers such as COL1A1, ALP, and RUNX2, under nesfatin-1 stimulation in vitro." (PMID 33344440, 2020). "Using quantitative real-time PCR (qRT-PCR), the collagens Col1A1, Col3A1 and Col5A2 were found to be significantly upregulated in the tendinopathies and chronic ruptures compared to the intact control and the acute ruptured tendons." (PMID 29385715, 2018). "In addition, a significant increase in the expression of Cox2, Mmp2, Mmp9, Col1a1, Col3a1, Vegf and Scx genes was also observed within the experimentally induced tendinopathy group compared with the control group." (PMID 33076550, 2020). "However, while the mRNA expression of a number of collagens was 1.6–2.7-fold upregulated in tendinopathy patients, COL1A1, COL1A2, COL10A1, and COL11A1/2 were 5.3–15.2-fold upregulated in tetraplegic CP patients, suggesting strongly increased collagen synthesis." (PMID 38001919, 2023). "Modulation in CTGF and COL1A1 gene expression has been previously reported after tendon perturbations such as exercise (net collagen degradation after 24–36 h followed by net synthesis by up to 72 h) and tendinopathies models (reduction in COL1A1 both 24 and 72 h of glutamate exposure)." (PMID 31551799, 2019). "In contrast, there was down-regulation of collagen type 1 α1 (COL1A1) in the tendinopathy cells compared to the healthy cells without statistical significance (p > 0.05)." (PMID 28598390, 2017). "Like the results from the earlier comparison of the healthy and tendinopathy tenocytes, the relative expression of COL1A1 showed no statistical difference between the PBS-control and SP-treated cells (p > 0.05) despite the observed decrease in the SP-treated group." (PMID 28598390, 2017).